TRBC2 (T cell receptor beta constant 2)
Description:
Constant region of T cell receptor (TR) beta chain. Alpha-beta T cell receptors are antigen specific receptors which are essential to the immune response and are present on the cell surface of T lymphocytes. Recognize peptide-major histocompatibility (MH) (pMH) complexes that are displayed by antigen presenting cells (APC), a prerequisite for efficient T cell adaptive immunity against pathogens. Binding of alpha-beta TR to pMH complex initiates TR-CD3 clustering on the cell surface and intracellular activation of LCK that phosphorylates the ITAM motifs of CD3G, CD3D, CD3E and CD247 enabling the recruitment of ZAP70. In turn, ZAP70 phosphorylates LAT, which recruits numerous signaling molecules to form the LAT signalosome. The LAT signalosome propagates signal branching to three major signaling pathways, the calcium, the mitogen-activated protein kinase (MAPK) kinase and the nuclear factor NF-kappa-B (NF-kB) pathways, leading to the mobilization of transcription factors that are critical for gene expression and essential for T cell growth and differentiation. The T cell repertoire is generated in the thymus, by V-(D)-J rearrangement. This repertoire is then shaped by intrathymic selection events to generate a peripheral T cell pool of self-MH restricted, non-autoaggressive T cells. Post-thymic interaction of alpha-beta TR with the pMH complexes shapes TR structural and functional avidity.
Synonyms: TCRBC2
Gene: T-cell receptor constant (C) gene on chromosome 7 (142,801,041 to 142,802,748, forward strand). Ensembl gene ENSG00000211772.
Subcellular location: Cell membrane
Homologues: Orthologues: mouse Trbc1 (79% identical), mouse Trbc2 (78% identical), rat AC109737.1 (52% identical). Paralogues in human: TRBC1 (96% identical), TRBV24-1 (11% identical), TRBV25-1 (11% identical), TRBV20-1 (10% identical), TRBV19 (9% identical), TRBV27 (9% identical), TRBV28 (9% identical), TRBV29-1 (9% identical), TRBV6-5 (9% identical), TRBV10-1 (9% identical), TRBV10-2 (9% identical), TRBV10-3 (9% identical), and 39 more.
Diseases named in the same sentence as TRBC2 in open-access papers:
TRBC2 is named in the same sentence as 20 diseases in open-access papers, as found by Europe PMC text mining. Sharing a sentence is not in itself a finding about the gene and the disease. The quoted sentences say what the papers report.
T-cell lymphomas (8 papers, 2019 to 2026). "Further, antigen escape by lineage switch between TRBC1 and TRBC2 is an unlikely scenario especially in mature T-cell lymphomas such as PTCL and ATCL, where the malignant cells have already undergone TCRβ rearrangement and commitment to allelic exclusion." (PMID 38383515, 2024). "One out of thirteen (7.7%) lymphoma samples showed some detectable TCRbeta1/TCRbeta2 protein co-expression, and 4 out of 13 (30.8%) T-cell lymphomas showed a TRBC1/TRBC2 transcript co-expression using BaseScopeTM." (PMID 39594145, 2024). "Development of a TRBC2 binder will now allow the possibility of targeting nearly all cases of mature T cell lymphomas, with TRBC1/2 based therapeutics opening the possibility of a widely applicable immunotherapeutic approach in this area of unmet medical need." (PMID 38383515, 2024). "The T cell receptor β-chain is expressed in two isoforms, TRBC1 and TRBC2, with clonally expanded mature T cell lymphomas expressing one of them exclusively, while healthy T cells randomly express either TRBC1 or TRBC2." (PMID 38383515, 2024). "Dual TRBC1/TRBC2 transcript expression appears to be more common in T-cell lymphomas (4/13 or 30.8% in our series) than kappa and lambda light chain co-expression in B-cell or plasma cell neoplasms." (PMID 39594145, 2024). "However, over 60% of T cell lymphomas are predicted to express TRBC2." (PMID 38383515, 2024). "All benign samples analyzed (immunohistochemically, by BaseScopeTM, by Q-PCR, and by RNAseq data analysis) had TCRbeta1/TCRbeta2 or TRBC1/TRBC2 ranges well within the previously published flow cytometric benign range (TCRbeta2/TCRbeta1 = 0.18:1–5.7:1), while samples of T-cell lymphoma did not." (PMID 39594145, 2024). "Therefore, this and the reciprocal TRBC2-specific approaches may benefit patients with peripheral T-cell lymphoma as well as a small fraction of T-ALL patients, without inducing complete T-cell ablation." (PMID 30891427, 2019). "A strategy to target TCRαβ on T cell lymphomas is in trial and relies on discriminatory targeting of TRBC1 or TRBC2, but would not be suitable to combine with CD3ε given their linked multimeric expression." (PMID 34035409, 2021).
lymphoma (3 papers, 2019 to 2025). A malignant (clonal) proliferation of B- lymphocytes or T- lymphocytes which involves the lymph nodes, bone marrow and/or extranodal sites. "Second, when performing TRBC1 flow cytometry, it is important to note that the TRBC1 assay is specifically applicable to αβ T cells, with limitations in assessing cells lacking surface TRBC1 or TRBC2 expression, such as γδ T cells, benign thymocytes, and surface CD3− lymphomas." (PMID 40521694, 2025).
melanoma (3 papers, 2021 to 2025). A malignant, usually aggressive tumor composed of atypical, neoplastic melanocytes. "Moreover, we analyzed the expression level of gene CD3E, CD4, CD8A, GZMB, NKG7, TCF7 and TRBC2, the well-known markers for CD8+ T cells, and they were all shown to have significantly higher expression level in melanoma patients with low risk." (PMID 34040608, 2021). "We defined clusters corresponding to melanoma (PMEL, MLANA), immune infiltrates (TRBC2, TRAC, TMSB4X), melanophages (CD74, LYZ), keratinocytes (KRT14, TRIM29), blood vessels (CAVIN1, PECAM), and fibroblast‐enriched areas in the dermis (DCN, COL1A2, FBLN1)." (PMID 39846232, 2025). "That neither TRBC2, CD4 nor CD8B expression within melanomas was predictive of a response to CPI therapies also supports a bona fide association of response with Vδ1+ cells." (PMID 38172341, 2024).
leukemia (2 papers, 2020 to 2022). A malignant (clonal) hematologic disorder, involving hematopoietic stem cells and characterized by the presence of primitive or atypical myeloid or lymphoid cells in the bone marrow and the blood. "Based on the mutually exclusive expression of TRBC1 and TRBC2, they developed anti-TRBC1 CAR-T cells that recognized and killed normal and malignant TRBC1+ but not TRBC2+ T cells in vitro and in a disseminated mouse model of leukemia." (PMID 35625998, 2022).
T-cell neoplasms (2 papers, 2024 to 2025). "The simple measure of TRBC1/TRBC2 could provide a simpler workflow for the identification of T-cell neoplasms." (PMID 40563694, 2025). "Importantly, 9 of the 13 mature T-cell neoplasms with dim TRBC1 expression (69%) were shown to be TRBC2-restricted on dual staining." (PMID 38424120, 2024). "We hereby introduce a novel strategy to identify TCRαβ T-cell neoplasms by flow cytometry, based on the restricted expression of TRBC1 or TRBC2." (PMID 38424120, 2024). "In addition, 5 of 38 (13%) mature T-cell neoplasms interpreted as TRBC1-negative on single staining (presumed TRBC2-restricted), were actually negative for both TRBC1 and TRBC2 using dual surface and intracellular staining." (PMID 38424120, 2024).
thymic epithelial tumors (1 paper, 2024). "To confirm this, we evaluated surface and cytoplasmic TRBC1 and TRBC2 expression (T-cell panel) on ten surgical biopsies harboring benign immature T-cell precursors (nine thymic epithelial tumors and one ectopic intrathyroidal thymic tissue)." (PMID 38424120, 2024).
cancer (8 papers, 2019 to 2025). A tumor composed of atypical neoplastic, often pleomorphic cells that invade other tissues. "Selective targeting of TRBC1 or TRBC2 enables the killing of cancer cells but preserves about 60-40% of the normal T cells." (PMID 41429932, 2025). "To enable such a therapy for cancers expressing TRBC2, here we developed a high-affinity anti-TRBC2 antibody." (PMID 41429932, 2025). "This permits generation of paired reagents (chimeric antigen receptor-T cells) specific for TRBC1 and TRBC2, with preclinical evidence to support their efficacy in T cell malignancies." (PMID 38383515, 2024). "However, the cancer T-cell population exclusively expresses either TRBC1 or TRBC2." (PMID 37753972, 2023). "T cell receptor β-chain constant (TRBC) is a promising class of cancer targets consisting of two highly homologous proteins, TRBC1 and TRBC2." (PMID 37753972, 2023).
tumor (7 papers, 2019 to 2026). "Both TRBC1-restricted and TRBC2-restricted tumors were observed in all disease categories studied, with an overall higher incidence of TRBC2+ neoplasms (73%, 95% CI: 60–83%) as expected by the slight overrepresentation of TRBC2 in the normal T-cell repertoire." (PMID 38424120, 2024).
bacterial infection (1 paper, 2023). "PRP also upregulated the genes involved in the beta chain of the T cell receptor (TRBV3‐1, TRBV6‐5, TRBV7‐2, TRBV27, TRBC2, and TRBJ2‐3), which is responsible for antigen recognition and activation of cellular immunity during bacterial infection." (PMID 36704119, 2023).
TRBC2 also shares sentences with these, for which no sentence is quoted: breast carcinoma (2 papers); lung carcinoma (2); plasma cell neoplasm (2); celiac disease (1); colorectal cancer (1); glioblastoma (1); glioma (1); infection (1); liver cancer (1); Lymphoid Tumour (1); pancreatic cancer (1).